ZNF407 (zinc finger protein 407)
Description:
May be involved in transcriptional regulation.
Synonyms: KIAA1703; FLJ20307; FLJ13839; SIMHA
Tractability: Antibody: the Human Protein Atlas places it where antibodies can reach. PROTAC: ubiquitination databases record sites on it.
Gene: Protein-coding gene on chromosome 18 (74,597,848 to 75,065,671, forward strand). Ensembl gene ENSG00000215421.
Subcellular location: Nucleus
Subcellular location (Human Protein Atlas): Nucleoplasm; Plasma membrane
Gene Ontology:
Molecular function: DNA-binding transcription factor activity; transcription cis-regulatory region binding; nucleic acid binding; zinc ion binding
Biological process: regulation of DNA-templated transcription
Cellular component: nucleus
Genetic constraint (gnomAD): Loss-of-function variants: 19 observed, 123.35 expected, observed/expected ratio (o/e) 0.15, 90% interval 0.11 to 0.23. The upper end of that interval is the gene's LOEUF score, 0.23, which puts it in group 1 of 6, group 1 being the genes least tolerant of losing a copy. Missense variants: 2,217 observed, 2,433.6 expected, observed/expected ratio (o/e) 0.91, 90% interval 0.88 to 0.94. Synonymous variants: 929 observed, 879.84 expected, observed/expected ratio (o/e) 1.06, 90% interval 1 to 1.12.
Homologues: Orthologues: chimpanzee ZNF407 (99% identical), macaque ZNF407 (96% identical), dog ZNF407 (78% identical), rat Zfp407 (75% identical), mouse Zfp407 (75% identical), rabbit ZNF407 (63% identical), tropical clawed frog znf407 (43% identical), zebrafish znf407 (20% identical). Paralogues in human: ZNF287 (8% identical), ZKSCAN7 (8% identical), ZNF527 (8% identical), ZNF214 (8% identical), ZNF572 (7% identical), ZBTB17 (7% identical), ZNF852 (7% identical), ZNF34 (7% identical), ZNF17 (7% identical), ZNF697 (7% identical), WIZ (7% identical), ZNF774 (7% identical), and 38 more.
Diseases named in the same sentence as ZNF407 in open-access papers:
ZNF407 is named in the same sentence as 14 diseases in open-access papers, as found by Europe PMC text mining. Sharing a sentence is not in itself a finding about the gene and the disease. The quoted sentences say what the papers report.
autism (3 papers, 2014 to 2024). Persistent deficits in social interaction and communication and interaction as well as a markedly restricted repertoire of activity and interest as well as repetitive patterns of behavior. "Another identified translocation breakpoint in the third intron of the ZNF407 gene causes a reduction in the transcript of its isoform 1, resulting in non-syndromic intellectual impairment and autism." (PMID 24907849, 2014). "Structural and missense variants in ZNF407 have been found in autism, OCD, and schizophrenia." (PMID 38891944, 2024).
Cognitive impairment (2 papers, 2014 to 2019). Abnormal cognition is characterized by deficits in thinking, reasoning, or remembering. "This is the first association of ZNF407 mutation to an autosomal recessive syndromic intellectual impairment/mental retardation detected using Whole Exome Sequencing of a single affected individual following the determination of specific gene mapping intervals through homozygosity mapping." (PMID 24907849, 2014). "Furthermore, two de novo damaging missense mutations [c.A1436G/p.Y460C; c.C3640G/p.P1195A] in the very long linker region between zinc fingers 3 and 4, and between 11 and 12, respectively, of the ZNF407 gene were found in one intellectual impairment patient each." (PMID 24907849, 2014).
Intellectual disability (2 papers, 2014 to 2022). "The deletion was the largest found in our dataset, spanning 13 Mb and two genes intolerant to truncating variants, ZNF236 and ZNF407 that were associated with chromosome 18q deletion syndrome (OMIM 601808), neurodevelopmental disorders, and intellectual disability, among others." (PMID 35678011, 2022).
schizophrenia (2 papers, 2022 to 2024). A major psychotic disorder characterized by abnormalities in the perception or expression of reality. "Genetic and methylation studies revealed associations in ZNF407 with neurodevelopmental disorders, schizophrenia as well as Gulf War illness." (PMID 35477560, 2022).
colon cancer (1 paper, 2018). "For example, WDR5 has been shown to promote EMT by promoting mesenchymal gene activation and binding to ZNF407 to promote colon cancer metastasis." (PMID 29925347, 2018).
congenital aural atresia (1 paper, 2014). "However, deletion of a critical region on 18q23 that includes the ZNF407 gene and two other zinc finger genes (ZNF516 and ZNF236), among other genes, is correlated with congenital aural atresia (CAA), which manifests a subset of phenotypes recognized by the 18q deletion (18q-) syndrome." (PMID 24907849, 2014).
Hearing impairment (1 paper, 2022). A decreased magnitude of the sensory perception of sound. "The region related to IgA deficiency and renal dysplasia is 18q22.3q23, and the gene related to hearing impairment and abnormal ear development is ZNF407." (PMID 36123715, 2022).
microcephaly (1 paper, 2021). A congenital or acquired developmental disorder in which the circumference of the head is smaller than normal for the person's age and sex. "Bi-allelic variants in CCDC88C were associated with a form of congenital hydrocephalus, while variants in ZNF407 have been recently implicated in an AR form of ID with microcephaly, short stature, hypotonia, and ocular anomalies." (PMID 34764295, 2021).
neurodevelopmental disorder (3 papers, 2021 to 2022). A behavioral and cognitive disorder with onset during the developmental period that involves impaired or aberrant development of intellectual, motor, or social functions. "In particular, we identified homozygous variants in CCDC88C (NM_001080414.4: c.1126 C > T, p.Arg376Trp) and ZNF407 (NM_017757.3: c.5497 > T, p.Pro1833Ser), two genes previously implicated in neurodevelopmental disorders but associated with phenotypes different than the one found in our proband." (PMID 34764295, 2021).
cancer (2 papers, 2015 to 2026). A tumor composed of atypical neoplastic, often pleomorphic cells that invade other tissues. "ZNF407 is a member of the large C2H2 (Krüppel) type zinc finger protein subfamily whose members have previously been implicated in cancer development." (PMID 26102504, 2015).
tumor (2 papers, 2015 to 2017). "Whilst the frameshift deletion in RNF146 seemed to be restricted to this particular tumour, a similar yet germline mutation in ZNF407 was found in a panel of 52 gastro-intestinal stromal tumours from different anatomical sites and different categories." (PMID 26102504, 2015). "We could not exclude a priori the possibility that any of the mutations in the relatively uncharacterised genes RNF146 or ZNF407 was linked to the formation of the tumor." (PMID 26102504, 2015). "Furthermore, gene expression microarrays were used to identify ZNF407, which was reported to affect tumor progression, as a novel target of WDR5, which markedly increased CRC cell migration." (PMID 28300833, 2017). "Besides these genetic lesions, only two point mutations that may affect tumour progression were identified: A frame-shift deletion in RNF146 and a missense mutation in a zinc finger of ZNF407." (PMID 26102504, 2015).
ZNF407 also shares sentences with these, for which no sentence is quoted: colorectal cancer (1 paper); gastrointestinal stromal tumor (1); renal dysplasia (1).